TBC1D3I (TBC1 domain family member 3I)
Description:
Acts as a GTPase activating protein for RAB5. Does not act on RAB4 or RAB11 (By similarity).
Synonyms: PRC17
Gene: Protein-coding gene on chromosome 17 (36,253,456 to 36,264,570, reverse strand). Ensembl gene ENSG00000274933.
Subcellular location: Cell membrane
Subcellular location (Human Protein Atlas): Vesicles
Gene Ontology:
Molecular function: GTPase activator activity
Cellular component: plasma membrane; endosome; membrane
Homologues: Orthologues: chimpanzee TBC1D3B (97% identical). Paralogues in human: TBC1D3D (99% identical), TBC1D3 (99% identical), TBC1D3C (99% identical), TBC1D3H (99% identical), TBC1D3L (99% identical), TBC1D3E (99% identical), TBC1D3F (99% identical), TBC1D3G (99% identical), TBC1D3K (99% identical), TBC1D3B (99% identical), TBC1D26 (30% identical), USP6NL (29% identical), and 33 more.